LEP (leptin)
Diseases named in the same sentence as LEP in open-access papers (continued):
Sharing a sentence is not in itself a finding about the gene and the disease.
asthma (continued). "We found that 5′-UTR LEP polymorphism (rs13228377) correlates with serum leptin levels, with AA genotype related to increased leptin level independent of asthma status, although the difference was marginally significant (P = 0.08)." (PMID 30203371, 2018). "Association of this variant with leptin serum level and lack of association between leptin receptor and its level in asthma were not published previously." (PMID 30203371, 2018). "However, leptin secretion stimulated upon asthma exacerbation suggests that also other than genetic regulatory elements influence its serum level during active airway inflammation process." (PMID 30203371, 2018). "In our previous study, we reported that childhood asthma is associated with polymorphism in leptin gene (LEP), but not with LEPR." (PMID 30203371, 2018). "To analyze if genotypes of LEP and LEPR polymorphisms together with their serum levels could be good predictors of asthma risk, we included them in the stepwise logistic regression analysis." (PMID 30203371, 2018). "In obese patients with adult-onset asthma, markers of metabolic inflammation, macrophage number, and leptin levels were increased in visceral fat when compared to obese controls and airway reactivity was significantly correlated to visceral fat leptin expression." (PMID 27212806, 2016). "An increased leptin/adiponectin ratio is associated with asthma compared to control subjects without asthma." (PMID 26770217, 2015). "The ability of leptin to upregulate leukotriene biosynthesis in alveolar macrophages may be particularly relevant to asthma given the potency of cysteinyl leukotrienes as bronchoconstrictors." (PMID 24288549, 2013). "Hypoxemia consequent to bronchoconstriction or systemic spillover of airway inflammation in severe asthma exacerbations may increase secretion of leptin from adipose tissue." (PMID 24288549, 2013). "Interestingly, the relationship between BMI and asthma remained unchanged even after adjusting for serum leptin concentration." (PMID 24025484, 2013). "Appetite-modulating hormones ghrelin and leptin might be relevant to asthma with their pro-inflammatory effects, and calprotectin has been recognized as a promising marker of inflammation." (PMID 24066855, 2013). "In particular, this review summarizes basic mechanistic data through population-based and clinical studies addressing the hypothesis that adiponectin, leptin, and possibly resistin may each have a role in asthma." (PMID 24288549, 2013). "The purpose of this study therefore was to explore whether asthma, atopy and lung functions have a relation with serum levels of leptin, ghrelin and calprotectin as inflammatory markers in children." (PMID 24066855, 2013). "Some but not all studies indicate that high serum leptin concentrations are associated with greater odds for asthma prevalence, particularly among prepubertal boys, peripubertal and postpubertal girls, and women." (PMID 24288549, 2013). "The influence of leptin on increasing asthma risks varied by gender has been reported." (PMID 24454412, 2013). "It has been hypothesized that high serum leptin levels precede airway inflammation, an important asthma characteristic." (PMID 24204876, 2013). "The purpose of this study was to explore whether asthma, atopy and lung functions has a relation with serum levels of leptin, ghrelin and calprotectin as inflammatory markers in children." (PMID 24066855, 2013). "Some studies suggest that leptin affects asthma also independently of body mass index (BMI)." (PMID 21615949, 2011). "In contrast, others have failed to document any direct association between leptin and the presence of asthma." (PMID 21040518, 2010). "Increasing evidence suggest that the pro-inflammatory effects of leptin may contribute to the higher incidence of asthma in the obese population." (PMID 21040518, 2010). "The results suggest that leptin has the potential to exacerbate asthma in the obese." (PMID 16581558, 2006).
asthma (continued). "Perhaps activating the TRPV4 channel on adipocytes or immune cells can reduce the secretion of leptin and adiponectin, prevent the content of adipocytokines in the surrounding blood, inhibit the occurrence of airway hyperresponsiveness, and ultimately achieve the goal of controlling asthma." (PMID 38365763, 2024). "Additionally, elevated leptin levels in OSA lead to increased bronchial airway hyperresponsiveness and inflammation, which might cause the exacerbation of asthma." (PMID 38310323, 2024). "Early monitoring and intervention of leptin may be needed for asthma." (PMID 36914629, 2023). "Finally, although a total of 59 studies were included in our studies, the number of studies regarding the difference of leptin level between severe and mild asthma among Caucasians was relatively small, which may decrease the statistical power." (PMID 36914629, 2023). "It indicated that leptin may be a risk predictor and prognostic marker of asthma independent of age and gender." (PMID 36914629, 2023). "Age and gender did not influence the association between leptin level and asthma risk/progression." (PMID 36914629, 2023). "In this regard, there may be a vital role of leptin in asthma with virus infection." (PMID 36551211, 2022). "Therefore, this study provides new insight into how leptin may directly affect lung inflammation and fibrosis in asthma." (PMID 35610699, 2022). "Interestingly, children with a poor control of asthma showed significantly higher leptin levels than controlled asthmatic children suggesting a role of leptin as a potential predictor for asthma control as previously hypothesized by other authors." (PMID 35055456, 2022). "However, the mechanism by which asthma appears to induce leptin synthesis remains to be elucidated." (PMID 35807067, 2022). "Additionally, it is possible that leptin administered subcutaneously could have effects on the central nervous system (CNS), which could then, in turn, impact asthma outcomes." (PMID 35610699, 2022). "However, the siRNA-mediated knockdown of Ob-R receptors in these cells suppresses the leptin-mediated upregulation of IL-6, CCL11, and IP-10, indicating that leptin can play a detrimental role in promoting inflammation in asthma patients by stimulating fibroblast differentiation." (PMID 35888038, 2022). "The main objective of our review is to address the knowns and unknowns of leptin on asthma." (PMID 36551211, 2022). "Furthermore, leptin upregulates leukotriene biosynthesis in alveolar macrophages, which may contribute to the pathogenesis of asthma." (PMID 35046816, 2021). "Leptin may induce inflammation in asthma by activation of Th2 cells." (PMID 30203371, 2018). "On the other hand, leptin may inhibit the function and proliferation of regulatory T-cells, which may impair the balance of Th1 and Th2 and promote the polarization of Th1-mediated autoimmune diseases and Th2-mediated immune diseases such as asthma." (PMID 30050954, 2018). "This hypothesis was confirmed by a recent study showing increased leptin levels in severe asthma." (PMID 30203371, 2018). "However, analysis of leptin level between asthmatic patients with different clinical condition (exacerbation vs. stable period) showed significantly increased leptin level during asthma exacerbation (P = 0.025)." (PMID 30203371, 2018). "However, although leptin levels were associated with asthma, it was not possible to rule out the possibility that this association was secondary to the association of both with fatness measures." (PMID 28696379, 2017). "Leptin also has profound effects on both innate and adaptive immune system that may impact asthma." (PMID 24288549, 2013). "In addition, high plasma leptin levels were associated with poorer lung function and increased symptoms suggesting that leptin is related to the severity of asthma also in non-obese patients." (PMID 21615949, 2011).
asthma (continued). "Additionally, studies have raised the issue whether leptin may play an important role on asthma pathophysiology through its ability to activate SNS." (PMID 21040518, 2010). "Furthermore, leptin levels, even when adjusted for BMI, are predictive of asthma in male subjects." (PMID 21040518, 2010). "Activating TRPM8 on adipose tissue cells can control the secretion of leptin and ADPN, reduce the levels of adipocytokines that promote airway inflammation, and help suppress asthma." (PMID 38365763, 2024). "Leptin, a small proline protein, and LAIR‐1 regulate ILC2s by targeting the PI3K‐AKT pathway, hence affecting the severity of asthma." (PMID 37357549, 2023). "However, the association between leptin status and asthma progression was not studied." (PMID 36914629, 2023). "Leptin can activate different signaling pathways that can induce asthma by promoting the proliferation of hybrid TH2/TH17 and TH17-like cells and decreasing T regulatory function by leptin-producing monocytes, resulting in a severe asthma phenotype." (PMID 37629427, 2023). "Interestingly, we found that age and gender did not affect the differences of leptin levels between asthma and non-asthma, as well as severe and mild asthma, which indicated that leptin status was associated with asthma risk/progression independent of age and gender." (PMID 36914629, 2023). "Several studies have demonstrated that leptin/IL6 signaling plays a critical role in inflammatory responses through activating STAT3, ultimately resulting in the pathogenesis of asthma." (PMID 36551211, 2022). "Previous studies have shown that the expression of leptin and TGF-β1 is inversely correlated in airway remodeling processes in asthma and allergic rhinitis." (PMID 34327205, 2021). "Thus, airway epithelial leptin signaling is speculated to be involved in asthma pathogenesis." (PMID 32512817, 2020). "Our current studies showed that HFD mice with plethoric leptin had increased TH2 and ILC2 proliferation and type 2 cytokine production compared with ND group, which contributes to the exacerbated asthma symptoms." (PMID 29891850, 2018). "The intervention group had significantly decreased body fat percent, visceral fat, weight, and BMI compared with the control group and displayed reduced leptin and CRP and improved asthma control and lung function." (PMID 30400197, 2018). "Secondary outcomes were other asthma features (asthma control, medication, asthma related QOL), lifestyle parameters (e.g. aerobic fitness), lung function indices, and inflammatory mediators (serum leptin and adiponectin)." (PMID 27294869, 2016). "Thus, leptin and adiponectin could have a role in the pathogenesis of asthma as supported by animal studies, and only few studies have been done in humans to convincingly establish a link between adipokines and asthma." (PMID 24454412, 2013). "Likely, the higher leptin production from subcutaneous fat rather than visceral fat, with greater values in females compared with males, may be the cause of a more serious status of asthma in obese women." (PMID 23157852, 2012). "On the basis of this conception, researchers have sought to determine the impact of leptin on specific respiratory disorders, including obstructive sleep apnoea-hypopnoea syndrome (OSAHS), asthma, chronic obstructive pulmonary disease (COPD) and lung cancer." (PMID 21040518, 2010). "Studies have shown that patients with asthma, especially its severe form, are characterized by higher leptin levels compared to patients without asthma." (PMID 40361972, 2025). "Our findings indicate that, at least inthe short term, high-dose ICSs do not significantly alter leptin levels or appetite in adults with stable asthma, including those who are overweight." (PMID 40710443, 2025). "The higher adiponectin/leptin ratio in non-obese asthma patients compared to obese asthmatic subjects was the only significant difference between the two groups." (PMID 38790590, 2024).
asthma (continued). "One study observation revealed a potential relationship between adiponectin and AD, i.e., obese children with asthma had higher leptin levels and lower adiponectin levels in serum than non-obese children with asthma." (PMID 39564133, 2024). "No significant causal relationships were found between leptin, sOB-R, resistin, RBP4, or PAI-1 and sarcoidosis, asthma, COPD, lung cancer, tuberculosis, pneumonia, and sleep apnea syndrome." (PMID 38263093, 2024). "We compared the differences of leptin level between asthma and non-asthma controls, as well as between severe and mild asthma cases." (PMID 36914629, 2023). "In clinical studies, obese patients with asthma had higher serum leptin levels and M1 macrophage polarization levels in induced sputum than non-obese patients with asthma." (PMID 37488474, 2023). "The Begg rank correlation test and Egger linear regression test indicated no significant publication bias among Caucasians in the difference of leptin status between asthma and non-asthma controls (Begg, p = 0.65; Egger, p = 0.994)." (PMID 36914629, 2023). "Particularly, expression of leptin and IL-6 appears to be increased in VAT of obese subjects with asthma, thus suggesting that these mediators could promote airway inflammation." (PMID 35806353, 2022). "The difference in leptin levels between patients with asthma and without asthma was not significant after budesonide treatment in 4 weeks." (PMID 36551211, 2022). "While atopic inflammation plays important roles in the onset of asthma, nonatopic inflammation (including leptin and adiponectin) aggravates the severity of the overweight/obese asthma phenotype." (PMID 35889925, 2022). "While atopic inflammation plays an important role in the onset of asthma, nonatopic inflammation (including leptin and adiponectin) increases the severity of asthma in overweight/obese patients." (PMID 35889925, 2022). "In the same study, the non-asthma group displayed sex differences in leptin levels, whereas no sex differences were observed in the asthma group." (PMID 35769576, 2022). "In-depth mechanistic studies on obese asthma are required to clarify the contributions of leptin, adiponectin, nonallergic systemic Th1 immune patterns, and Th2 inflammation, respectively." (PMID 35889925, 2022). "In keeping with previous observations, our study also found higher leptin levels in asthma patients—particularly in non-atopic patients—and obese subjects than in healthy control individuals." (PMID 35807067, 2022). "Moreover, the inflammation promoted by adipocytes has been increased in obese subjects with asthma due to the release of pro-inflammatory mediators, such as IL-6, TNF-a, or leptin, and the downregulation of anti-inflammatory factors, including adiponectin." (PMID 36613991, 2022). "Another notable similarity between these studies is that exogenous leptin administration did not alter BAL eosinophil levels induced by the respective asthma models, but exogenous leptin did significantly decrease BAL IL-5 levels." (PMID 35610699, 2022). "Changes in leptin and adiponectin protein levels in airways were similar to those found in adipose tissue: At baseline leptin levels were higher, and adiponectin lower in BALF of participants with asthma compared with control subjects." (PMID 33418879, 2021). "Onthe other hand, the mean values of leptin were significantly higher in the obesegroup than in other participants, regardless of the presence of asthma (p<0.001).These results remained significant when we analyzed boys (p<0.001) and girls(p=0.018) separately." (PMID 33175004, 2020). "Nevertheless, elevated leptin values in the same study were positively correlated with high levels of interferon (INF)-g (Th1 cytokine) that were attributed to inflammation around the bronchioles and the aggravation of severe asthma." (PMID 32143340, 2020).
asthma (continued). "Besides, Youssef et al54 showed greater involvement of leptin, a metabolic regulator, in obese asthma patients as compared with non‐obese children, manifesting Th1 bias, higher IFN‐γ levels and greater asthma severity." (PMID 30450768, 2019). "A negative association between higher levels of leptin or leptin/adiponectin ratio with lung function could also be mediated by increased systemic inflammation, supported by studies showing an association between adiposity and clinical asthma in childhood and adulthood." (PMID 29351745, 2018). "In nonobese women with adult-onset asthma, leptin correlated negatively with lung function and positively with asthma symptom score, after adjusting for BMI." (PMID 27212806, 2016). "In nonobese women with adult-onset asthma, leptin correlated positively with asthma symptom score and negatively with lung function when adjusted for BMI." (PMID 26538828, 2015). "Serum levels of leptin increase while the levels of adiponectin decrease with increasing BMI but leptin has not been consistently shown to be increased in childhood- or adult-onset asthma when adjusted to BMI." (PMID 26538828, 2015). "Leptin levels in female asthmatics were 31.6 ± 24.1 compared to females without asthma 20.9 ± 3.7 ng/mL, p = 0.03." (PMID 26770217, 2015). "ANOVA demonstrated that leptin/adiponectin ratio was significantly different between the four groups: obese asthmatics, nonasthma nonobese, asthma nonobese, and nonasthma obese." (PMID 26770217, 2015). "Leptin levels in men with and without asthma were 13.1 ± 11.9 and 11.7 ± 8.5 ng/mL, respectively (p = 0.29)." (PMID 26770217, 2015). "There was no decline in leptin levels in asthma with age, in postmenopausal compared to premenopausal subjects matched for BMI." (PMID 26770217, 2015). "Using ANOVA, leptin was significantly different between the four groups: obese asthmatics, nonasthma nonobese, asthma nonobese, and nonasthma obese." (PMID 26770217, 2015). "The impact of reduced serum adiponectin levels in humans with asthma is, like leptin, not clearly defined." (PMID 26770217, 2015). "Primary alveolar macrophages derived from overweight/obese adults with asthma generated greater levels of proinflammatory cytokines (such as IL-8 and TNF-α) after stimulation with leptin than macrophages derived from either normal weight asthmatics or obese nonasthmatics." (PMID 24288549, 2013). "Our understanding of the effect of leptin on asthma in humans, independent of the confounding effect of BMI, is therefore still evolving." (PMID 24288549, 2013). "The adiponectin/leptin ratio is a new IR marker that has been shown to be useful in studies of people with cardiovascular disease, but there is not much evidence that it can be used in people with asthma." (PMID 40361972, 2025). "However, the present study did not include healthy controls to verify the mechanism of leptin involvement in asthma." (PMID 40083433, 2025). "In addition, significantly higher leptin levels have been demonstrated in people with asthma compared to controls (p < 0.01), regardless of gender and age." (PMID 40095561, 2025). "Additionally, elevated leptin levels enhanced the activation of Th17 cells, contributing to the neutrophilic inflammation specific for non-eosinophilic obesity-related asthma." (PMID 41156032, 2025). "Children with asthma had higher levels of IL-2 (p = 0.005), IL-5 (p < 0.001), IL-13 (p = 0.021), IL-17A (p < 0.001), IL-22 (p < 0.001), IL-33 (p < 0.001), TNF-α (p < 0.001), and lower levels of IL-10 (p = 0.046) and leptin (p < 0.001) compared to those without asthma." (PMID 39902293, 2024). "Lepin may influence the lung function, Which was consistent with our findings that leptin staus was higher in the asthma cases compared with non-asthma controls, as well as in severe asthma compared with mild asthma cases." (PMID 36914629, 2023).